GDF6 (growth differentiation factor 6)
Diseases named in the same sentence as GDF6 in open-access papers (continued):
Sharing a sentence is not in itself a finding about the gene and the disease.
colon adenocarcinoma (2 papers, 2022 to 2025). "For GDF6, there are 2 colon adenocarcinoma mutations, 1 in β8Cys4 (Cys230Arg) and 1 in the ligand (Cys419Tyr)." (PMID 36214621, 2022). "Analysis of β8 region cysteines began with GDF6 β8Cys@4 (Cys230Arg) that is found in colon adenocarcinomas." (PMID 36214621, 2022). "Similarly, the CN-high subtype of uterine corpus endometrial carcinoma (UCEC) and the chromosomal instability (CIN) subtype of colon adenocarcinoma/rectum adenocarcinoma (COADREAD) present notable GDF6 amplification." (PMID 40699648, 2025).
colorectal cancer (2 papers, 2025). A primary or metastatic malignant neoplasm that affects the colon or rectum. "In this study, we found that GDF6 expression was significantly positively correlated with tumor mutational burden (TMB) in colorectal cancer (COAD), microsatellite instability (MSI) in testicular germ cell tumors (TGCT), and homologous recombination deficiency (HRD) in lung adenocarcinoma (LUAD)." (PMID 40699648, 2025). "In colorectal cancer, the high methylation of the GDF6 promoter leads to its transcriptional silence, suggesting that epigenetic silencing may mediate the inactivation of tumor-suppressor functions." (PMID 40699648, 2025).
Leber congenital amaurosis (2 papers, 2014 to 2020). Leber congenital amaurosis (LCA) is a retinal dystrophy defined by blindness and responses to electrophysiological stimulation (Ganzfeld electroretinogram (ERG)) below threshold, associated with severe visual impairment within the first year of life. "Mutations in GDF6 were recently found to be associated with age-related macular degeneration and Leber's congenital amaurosis, both representing photoreceptor degenerative disease." (PMID 24681822, 2014).
osteosarcoma (2 papers, 2017 to 2020). A usually aggressive malignant bone-forming mesenchymal neoplasm, predominantly affecting adolescents and young adults. "Consistent with GDF6 being an EWS-FLI1 target, GDF6 is highly expressed in Ewing sarcoma tumors and cell lines compared with mesenchymal stem cells, rhabdomyosarcoma cells, osteosarcoma cells, synovial sarcoma cells, and epithelial cells, such as 293, 293T, HeLa, and HCT116." (PMID 33147457, 2020). "The opposing activities of Src detected in the osteosarcoma study and the present study may reflect the different sarcoma types or different experimental conditions employed (CD99 exogenous expression in osteosarcoma versus endogenous GDF6 silencing in Ewing sarcoma)." (PMID 33147457, 2020).
breast carcinoma (1 paper, 2025). "In the Anti-PD1 cohort, derived from breast cancer patients treated with Paclitaxel + Pembrolizumab, high GDF6 expression was found to be associated with treatment resistance (AUC = 0.643)." (PMID 40699648, 2025). "In breast cancer (BRCA), the Basal and Her2 subtypes show marked GDF6 upregulation, while in glioma (GBM), the Classical and Mesenchymal subtypes display frequent gains." (PMID 40699648, 2025). "Notably, GDF6 was positively correlated with the stemness index in low-grade glioma (LGG), while it was negatively correlated in breast cancer (BRCA), suggesting that it may regulate tumor stem cell characteristics through tissue-specific pathways, such as the WNT or NOTCH pathways." (PMID 40699648, 2025).
breast invasive carcinoma (1 paper, 2025). "GDF6 was significantly downregulated in 23 types of tumors, including glioblastoma multiforme (GBM) and breast invasive carcinoma (BRCA), while it was abnormally upregulated in seven types of tumors, such as kidney renal clear cell carcinoma (KIRC) and pancreatic adenocarcinoma (PAAD)." (PMID 40699648, 2025).
cardiac hypertrophy (1 paper, 2025). "Gain- and loss-of-function studies indicate that GDF6 knockdown aggravates, while GDF6 overexpression attenuates, pressure overload-induced cardiac hypertrophy, inflammation, and dysfunction in vivo and in vitro." (PMID 41462947, 2025). "These in vivo and in vitro data identified the safety of GDF6 manipulation for the treatment of cardiac hypertrophy and heart failure." (PMID 41462947, 2025). "Echocardiographic analysis also determined significant elevations of IVSd and IVSs in GDF6-silenced hearts, indicating exacerbated cardiac hypertrophy." (PMID 41462947, 2025). "Taken together, our data reveal that GDF6 overexpression attenuates pressure overload-induced cardiac hypertrophy and dysfunction." (PMID 41462947, 2025). "Our study implies that GDF6 ameliorates cardiac hypertrophy through activating AMPKα in vivo and in vitro." (PMID 41462947, 2025). "In the present study, we established TAC-induced cardiac hypertrophy in mice and PE-induced hypertrophic growth of NRVMs, and detected an elevated GDF6 expression in murine hearts and NRVMs under hypertrophic stimuli." (PMID 41462947, 2025). "Collectively, we demonstrate that GDF6 knockdown aggravates pressure overload-induced cardiac hypertrophy and dysfunction." (PMID 41462947, 2025). "GDF6 knockdown aggravated, while GDF6 overexpression attenuated, pressure overload-induced cardiac hypertrophy, inflammation, and dysfunction in vivo." (PMID 41462947, 2025). "Echocardiographic analysis also determined significant decreases in the IVSd and IVSs in GDF6-overexpressed hearts, which indicates an improved cardiac hypertrophy." (PMID 41462947, 2025). "GDF6 knockdown aggravated, while GDF6 overexpression attenuated, pressure overload-induced cardiac hypertrophy and dysfunction in vivo." (PMID 41462947, 2025). "Meanwhile, echocardiographic analysis also revealed that CpC treatment significantly blocked GDF6 overexpression-mediated protective effects against ventricular hypertrophy, dilation, and dysfunction, as evidenced by decreased FS and increased LVEDd, LVEDs, IVSd, and IVSs." (PMID 41462947, 2025). "Growth differentiation factor 6 (GDF6) plays critical roles in cell growth and cardiovascular homeostasis; however, its role and underlying mechanisms in cardiac hypertrophy remain unclear." (PMID 41462947, 2025). "In summary, our findings, for the first time, define GDF6 as a negative regulator of cardiac hypertrophy and show that supplementation of GDF6 may be of great therapeutic interest for heart failure." (PMID 41462947, 2025). "Second, whether GDF6 expressed by other cardiac cells also prevents pressure overload-induced cardiac hypertrophy and heart failure should be determined in further studies." (PMID 41462947, 2025). "To explore the involvement of GDF6 in the pathogenesis of cardiac hypertrophy, we first determined whether GDF6 expression was altered during cardiac hypertrophy." (PMID 41462947, 2025). "AMPKα is an attractive molecular target to treat cardiac hypertrophy, and we herein investigated whether it was required for GDF6-mediated protection against cardiac hypertrophy." (PMID 41462947, 2025). "The present study tries to overexpress and knock down GDF6 in murine hearts using adeno-associated virus serotype 9 (AAV9) and then establishes transverse aortic constriction (TAC)-induced cardiac hypertrophy to decipher its role in pressure overload-induced cardiac hypertrophy and dysfunction." (PMID 41462947, 2025). "In general, our findings, for the first time, define GDF6 as a negative regulator cardiac hypertrophy and show that supplementation of GDF6 may be of great therapeutic interest for heart failure." (PMID 41462947, 2025). "Therefore, we detected whether ROS production contributed to increased GDF6 expression during cardiac hypertrophy by using the NADPH oxidase inhibitor APO or the ROS scavenger NAC." (PMID 41462947, 2025).
cardiac hypertrophy (continued). "Further studies showed that GDF6 activated AMPKα through the cAMP/Epac1 pathway, and that Epac1 knockdown abolished the protective effects of GDF6 against TAC- or PE-induced cardiac hypertrophy in vivo and in vitro." (PMID 41462947, 2025). "In this study, we observed a significant upregulation of GDF6 in hypertrophic hearts and NRVMs, and that GDF6 overexpression or supplementation effectively blocked TAC- or PE-induced cardiac hypertrophy in vivo and in vitro." (PMID 41462947, 2025). "In general, our findings, for the first time, define GDF6 as a negative regulator of cardiac hypertrophy and show that supplementation of GDF6 with viral/non-viral vectors or systemic administration with nanoparticles may be of great therapeutic interest for heart failure." (PMID 41462947, 2025).
cleft palate (1 paper, 2015). Cleft palate is a fissure type embryopathy that affects the soft and hard palate to varying degrees. "For these two groups, rs227731 (17q22), rs8610209 (IRF6), and rs2514527 (GDF6) were selected as risk predictors for cleft palate-soft only, whereas rs2073485 (IRF6), rs17389541 (IRF6), and rs1530300 (8q24) jointly contributed to the risk of cleft palate-hard." (PMID 26322076, 2015).
disc degeneration (1 paper, 2025). "For example, current leading candidate factors for mobilizing endogenous stem cells to repair IVD tissue include BMP13 or GDF6, as well as potential drugs regulating inflammation in disc degeneration, such as CGS-21680 (an A2AR agonist)." (PMID 41163783, 2025).
dwarfism (1 paper, 2022). "These genes were mainly involved in bone resorption (e.g., PTGER4), bone mineralization (e.g., BMP6), and dwarfism (e.g., GDF6 and PTDSS1)." (PMID 34893856, 2022).
endometrial cancer (1 paper, 2025). Primary or metastatic malignant neoplasm involving the endometrium (mucous membrane that lines the endometrial cavity). "Further clinical correlation analysis indicated that high GDF6 expression was significantly associated with advanced pathological stages and poor prognosis in endometrial cancer (UCEC) and gastric adenocarcinoma (STAD)." (PMID 40699648, 2025).
esophageal carcinoma (1 paper, 2025). A primary or metastatic malignant neoplasm involving the esophagus. "In solid tumors such as mesothelioma (MESO) and esophageal carcinoma (ESCA), high expression of GDF6 was significantly positively correlated with the infiltration of myeloid derived suppressor cells (MDSCs) and cancer associated fibroblasts (CAFs), showing pro-immunosuppressive effects." (PMID 40699648, 2025).
leukemia (1 paper, 2025). A malignant (clonal) hematologic disorder, involving hematopoietic stem cells and characterized by the presence of primitive or atypical myeloid or lymphoid cells in the bone marrow and the blood. "MSC also secrete a number of cytokines, chemokines, and growth factors (e.g., VEGFC, TGF‐β1, TGF‐ β2, GDF6, SDF1, and IL‐6) that can further modulate the interaction between leukemia cells and MSC." (PMID 40682336, 2025).
multiple synostoses syndrome (1 paper, 2025). Multiple synostoses syndrome (MSS) is a rare developmental bone disorder characterized by proximal symphalangism of the fingers and/or toes often associated with fusion of carpal and tarsal, humeroradial, and cervical spine joints. "Thus, proximal interphalangeal fusion is typically observed in multiple synostoses syndrome linked to NOG, GDF5 and FGF9 genes, while fusion of carpal and tarsal bones is observed in patients carrying a GDF6 variant." (PMID 40673520, 2025).
neuropathies (1 paper, 2014). "The synthesis of this data combines with recent reports of a role for GDF6 in congenital and late-onset photoreceptor degenerations to compel a role for GDF6 as a modifier gene in the etiology of disparate neuropathies." (PMID 24586579, 2014).
otosclerosis (1 paper, 2021). Formation of spongy bone in the labyrinth capsule which can progress toward the stapes (stapedial fixation) or anteriorly toward the cochlea leading to conductive, sensorineural, or mixed hearing loss. "GDF6 gain-of-function mutations cause multiple synostoses syndrome type 4 (SYNS4) which is characterised by synostoses of the carpals and tarsals and otosclerosis-associated conductive hearing loss but not vertebral fusion." (PMID 34573339, 2021).
ovarian carcinoma (1 paper, 2025). A malignant neoplasm originating from the surface ovarian epithelium. "In ovarian cancer (OV), the amplification of chromosome 8q22.1 drives the overexpression of GDF6, which may promote metastasis by activating the BMP/Smad pathway." (PMID 40699648, 2025).
radiculopathy (1 paper, 2023). Disease involving a spinal nerve root (see spinal nerve roots) which may result from compression related to intervertebral disk displacement; spinal cord injuries; spinal diseases; and other conditions. "Evaluation of GDF6 on: (i) gene expression of inflammatory/pain‐related molecules and structural integrity in a rabbit IVDD model, and (ii) sensory dysfunctional changes leading to pain‐marker expression in a rat DRG xenograft radiculopathy model." (PMID 36994466, 2023).
renal agenesis (1 paper, 2020). Renal agenesis (RA) is a form of renal tract malformation characterized by the complete absence of development of one or both kidneys (unilateral RA or bilateral RA respectively), accompanied by absent ureter(s). "This proposal is in line with the spectrum of renal abnormalities seen in GDF6 variant carriers that includes renal agenesis and renal hypodysplasia (two cases here), two anomalies also found in patients carrying BMP4 variants." (PMID 32737436, 2020).
renal anomaly (1 paper, 2020). "The phenotype spectrum identified in renal anomaly patients with GDF6 variants ranged from hypodysplasia to fusion." (PMID 32737436, 2020). "In this context, it is notable that we detected one GDF6 variant, the missense variant c.746C>A, recurrently in renal anomaly patients, resulting in a significant frequency increase compared with the cohort of the 1000 Genomes Project." (PMID 32737436, 2020). "Interestingly, 74% of the GDF6 variants detected in patients with different phenotypes, including the recurrent c.746C>A variant and the c.112G>C variant identified in renal anomaly patients here, affect amino acids located in the prodomain of the GDF6 sequence." (PMID 32737436, 2020). "Accordingly, the percentage of rare GDF6 variants in patients with renal plus bone, eye, or ear abnormalities was 5.4%, significantly higher than in renal anomaly patients without these extrarenal manifestations." (PMID 32737436, 2020).
renal dysplasia (1 paper, 2020). Renal dysplasia is a form of renal malformation in which the kidney(s) are present but their development is abnormal and incomplete. "This is exemplified by a family with Stickler syndrome and a heterozygous nonsense variant in the BMP4 gene encoding bone morphogenetic protein 4, a ligand related to GDF6, with renal dysplasia in only one of five family members carrying the BMP4 variant." (PMID 32737436, 2020).
renal malformations (1 paper, 2020). "In the present study systematically investigating a role of GDF6 in renal anomalies, we identified rare heterozygous GDF6 variants in 1.6% of patients with kidney malformations." (PMID 32737436, 2020). "Having identified a GDF6 variant previously associated with skeletal and ocular anomalies in a patient presenting with these phenotypes and additionally with a renal malformation, we explored the frequency of rare GDF6 variants in a cohort of patients with renal anomalies." (PMID 32737436, 2020). "Therefore, in GDF6 variant carriers reduced penetrance for renal malformations may be explained by the complexity of TGF-β signaling comprising numerous ligands (around 30), receptors, and downstream interacting proteins, suggesting some redundancy." (PMID 32737436, 2020).
renal papillary cell carcinoma (1 paper, 2025). "Especially in renal papillary cell carcinoma (KIRP), the overall survival period of patients with high GDF6 expression was significantly shortened." (PMID 40699648, 2025).
Septo-optic dysplasia (1 paper, 2012). Septooptic dysplasia (SOD) is a clinically heterogeneous disorder characterized by the classical triad of optic nerve hypoplasia, pituitary hormone abnormalities and midline brain defects. "Furthermore, we are able to confirm previous results that the Vax1 gene is involved in Septo-Optic Dysplasia and suggest Gdf6 and Marcks as further potential candidates." (PMID 22719993, 2012). "Furthermore, we are able to provide evidence that Vax1 (MGI:1277163) is involved in Septo-Optic Dysplasia (OMIM:#182230) and suggest Gdf6 (MGI:95689) and Marcks (MGI:96907) as novel candidates." (PMID 22719993, 2012).
tendinopathy (1 paper, 2025). "Autologous mesenchymal/stromal stem cells (MSCs) and tendon-derived stem cells (TSCs), combined with growth factors (GFs) like GDF-5, GDF-6 and GDF-7, are emerging as potential therapies for tendinopathy." (PMID 40395976, 2025).
uterine carcinosarcoma (1 paper, 2025). A usually aggressive malignant neoplasm arising from the uterine corpus and less often the cervix. "Based on the mutation spectrum analysis of GDF6 in the TCGA pan-cancer dataset, GDF6 was found to have somatic mutations in 32 types of cancer, with the highest mutation frequency in uterine carcinosarcoma (UCS) at 12.28%." (PMID 40699648, 2025).